SPARCL1 (SPARC like 1)
Synonyms: MAST9; MAST 9; PIG33; SC1
Tractability: Antibody: UniProt places it where antibodies can reach, with medium confidence; UniProt predicts a signal peptide or a membrane-spanning region; its Gene Ontology location is reachable by antibodies, with medium confidence. PROTAC: ubiquitination databases record sites on it.
Gene: Protein-coding gene on chromosome 4 (87,473,329 to 87,531,118, reverse strand). Ensembl gene ENSG00000152583.
Subcellular location: Secreted, extracellular space, extracellular matrix
Pathways (Reactome):
Metabolism of proteins: Post-translational protein phosphorylation; Regulation of Insulin-like Growth Factor (IGF) transport and uptake by Insulin-like Growth Factor Binding Proteins (IGFBPs)
Gene Ontology:
Molecular function: protein binding; calcium ion binding
Biological process: regulation of synapse organization; signal transduction; synaptic membrane adhesion
Cellular component: extracellular region; endoplasmic reticulum lumen; extracellular matrix; non-collagenous component of interstitial matrix; glutamatergic synapse
Genetic constraint (gnomAD): Loss-of-function variants: 41 observed, 57.09 expected, observed/expected ratio (o/e) 0.72, 90% interval 0.56 to 0.93. The synonymous counts are far from expectation, so gnomAD's model fits this gene poorly and the ratio says little. Missense variants: 668 observed, 755.42 expected, observed/expected ratio (o/e) 0.88, 90% interval 0.83 to 0.94. Synonymous variants: 209 observed, 267.55 expected, observed/expected ratio (o/e) 0.78, 90% interval 0.7 to 0.88.
Homologues: Orthologues: chimpanzee SPARCL1 (98% identical), macaque SPARCL1 (92% identical), rabbit SPARCL1 (76% identical), dog SPARCL1 (76% identical), pig SPARCL1 (72% identical), guinea pig SPARCL1 (72% identical), mouse Sparcl1 (65% identical), rat Sparcl1 (64% identical), zebrafish sparcl1 (28% identical), Drosophila melanogaster SPARC (14% identical), Caenorhabditis elegans ost-1 (14% identical). Paralogues in human: SPARC (24% identical).
Diseases named in the same sentence as SPARCL1 in open-access papers:
SPARCL1 is named in the same sentence as 126 diseases in open-access papers, as found by Europe PMC text mining. Sharing a sentence is not in itself a finding about the gene and the disease. The quoted sentences say what the papers report.
colorectal cancer (13 papers, 2017 to 2024). A primary or metastatic malignant neoplasm that affects the colon or rectum. "In colorectal cancer, upregulation of SPARCL1 has been associated with favourable survival outcomes, while downregulation of SPARCL1 is observed in more aggressive cases." (PMID 39548034, 2024). "SPARCL1 was significantly downregulated and was associated with tumor stage, distant metastasis, and OS in colorectal cancer." (PMID 36483097, 2022). "Reduced expressed SPARCL1 has been related to favourable prognosis in colorectal cancer, while its upregulation in tumour vessel endothelial cells has been linked to better survival in colorectal carcinoma." (PMID 39548034, 2024). "Moreover, SPARCL1 has been shown to impede motility in colorectal carcinoma and is linked to tumour stage and metastasis." (PMID 39548034, 2024). "Future studies should elucidate whether the preferential loss of SPARCL1 in various malignomas is due to its function as a vascular-derived tumor suppressor favouring vessel homeostasis, as reported for colorectal carcinoma." (PMID 32437418, 2020). "The expression of SPARCL1 is downregulated in colorectal cancer and is related to tumor differentiation, stage, distant metastasis, and OS." (PMID 37180578, 2023). "SPARCL1 expression in colorectal cancer(CRC) liver metastasis is downregulated, with SPARCL1 being considered the hub gene of liver metastasis and a biomarker with a significant prognostic value." (PMID 37180578, 2023). "SPARCL1 was a prognostic biomarker for colorectal cancer because its expression was downregulated through DNA methylation." (PMID 37563710, 2023). "Similar results were obtained in colorectal cancer, which suggested that SPARCL1 inhibited tumor migration and invasion in colorectal cancer and predicted better survival." (PMID 36483097, 2022). "We aim to evaluate the clinical significance and potential biological roles of SPARCL1 in colorectal cancer (CRC)." (PMID 35111844, 2022). "It has been found that Sparcl1 is frequently downregulated in many cancers, including colorectal carcinoma, prostate cancers, pancreatic cancer, etc., suggesting its potential role as a tumor suppressor." (PMID 36387870, 2022). "SPARCL1 is a matricellular protein with anti-adhesive, anti-proliferative and anti-tumorigenic functions and is frequently downregulated in tumors such as colorectal carcinoma or non-small cell lung cancer." (PMID 32437418, 2020). "A Swedish research team reported that over-expression of SPARCL1 protein in the primary colorectal carcinomas had a short survival, while the diametrically opposing conclusions were drawn by Hu and colleagues through western blot and immunohistochemistry." (PMID 29973149, 2018). "Notably, SPARCL1 is downregulated in various cancer types, including colorectal carcinoma and prostate carcinoma." (PMID 39548034, 2024). "Studies have identified SPARCL1 as an angiocrine tumor suppressor secreted by tumor vessel endothelial cells, thereby exerting inhibitory activity on angiogenesis and tumor growth, in colorectal carcinoma." (PMID 32437418, 2020). "In agreement with the initial isolation of human SPARCL1 (hSPARCL1) from high endothelial venules, subsequent publications showed that hSPARCL1 expression in different tumors, including colorectal carcinoma (CRC), is highly associated with blood vessel endothelial cells." (PMID 32437418, 2020). "Notably, it has been established that SPARCL1 is reduced in colorectal cancer." (PMID 39548034, 2024). "SPARCL1 may prevent the activity of colorectal cancer through its DNA methylation." (PMID 35281077, 2022). "Similarly, higher expression of SPARCL1 was correlated with better cell differentiation and less distant metastasis in colorectal cancers than those with lower expression of SPARCL1, and SPARCL1 was positively correlated with the prognosis of colorectal cancers (P < 0.01)." (PMID 33980221, 2021).
colorectal cancer (continued). "In addition, SPARCL1 may also promote differentiation possibly via mesenchymal-epithelial transition, which inhibits the aggressiveness of colorectal cancer." (PMID 29973149, 2018).
glioma (10 papers, 2013 to 2026). A benign or malignant brain and spinal cord tumor that arises from glial cells (astrocytes, oligodendrocytes, ependymal cells). "Bulk RNA sequencing showed high SPARCL1 expression in low-grade gliomas, which is consistent with astrocytic lineage, IDH mutation, and spatial averaging effects that might obscure regional associations." (PMID 42123596, 2026). "Moreover, SPARCL-1 expression has been previously associated with gliomas and the proliferative potential of glioma cancer stem cells." (PMID 37627098, 2023). "Enrichment of SPARCl1 at invasive tumor margins is consistent with prior studies linking SPARCL1 to neuron-glioma synapse formation and angiogenesis." (PMID 42123596, 2026). "While SPARCL1 is downregulated in many peripheral cancers, reports of its expression in gliomas, specifically glioblastoma (GBM), are inconsistent." (PMID 42123596, 2026). "It is known that the protein complex of HSP90B with PTN, SPARC, and SPARCL1 facilitates the migration of glioma cells." (PMID 36033456, 2022). "SOX9 and HEY2, TFs associated with glioma stemness, were highly expressed in the Glioma-SPARCL1 population, suggesting that this population might consist of glioma stem cells." (PMID 38515213, 2024). "Protein complex, containing PTN, SPARC, SPARCL1, and HSP90B, facilitates the migration of glioma cells." (PMID 36033456, 2022).
breast carcinoma (9 papers, 2014 to 2024). "Analysis of microarray data revealed that up-regulated SPARCL1 was linked with a good prognosis in lung and breast cancer." (PMID 36483097, 2022). "In recent years, a multitude of studies have reported that SPARCL1 implicated in the initiation and progression of various cancer, including prostate, colorectal, gastric, liver, breast cancer." (PMID 29973149, 2018). "Similarly, secreted protein acidic and rich in cysteine-like protein 1 (SPARCL1) was another ECM-glycoprotein whose reduced expression was reported in human breast cancer tissues, and NVA-AA NP treatment caused an increase in the SPARCL1 expression." (PMID 37719007, 2023). "It has also been considered a tumor suppressor as well as an oncogene; thus, altered regulation of SPARCL1 after treatment can be useful in implicating it as a therapeutic target in breast cancer." (PMID 37719007, 2023). "Decreased SPARCL1 expression has been reported in gastric cancer, liver cancer, cholangiocarcinoma, pancreatic cancer, breast cancer, and prostate cancer." (PMID 35111844, 2022). "Three breast cancer cohorts demonstrated that patients with increased SPARCL1 have a better prognosis (GSE 9195, RFS HR = 0.31, Cox p = 0.003; GSE1456-GPL96, OS HR = 0.45, Cox p < 0.001; GSE12276, RFS HR = 0.73, Cox p = 0.004)." (PMID 36483097, 2022). "Intriguingly, highly expressed SPARCL1 was related to good prognosis in lung and breast cancer based on Kaplan-Meier plotter database (HR = 0.68, p = 3.9e-09 and HR = 0.62, p = 1.3e-05, respectively)." (PMID 36483097, 2022). "Consistent with the notion that spinal astrocytes contribute to the pathogenesis of paclitaxel‐induced painful neuropathy, we showed that paclitaxel‐induced mechanical allodynia in naive and breast cancer‐bearing mice significantly increased levels of astrocyte‐secreted Sparcl1." (PMID 39126272, 2024). "We suppose that SPARCL1 may primarily influence survival through its involvement in determining breast cancer subtypes." (PMID 37180578, 2023).
prostate carcinoma (9 papers, 2017 to 2024). A carcinoma that arises from epithelial cells of the prostate gland. "SPARCL1 is also downregulated in prostate cancer, being associated with disease progression, especially in invasive prostate cancer." (PMID 37180578, 2023). "CTCs also demonstrated low SPARCL1 expression, a feature that has been associated with metastasis in prostate cancer." (PMID 27494900, 2017). "High expression of SPARCL1 in prostate cancer is associated with better survival, 5 year metastatic disease-free survival of men with loss of SPARCL1 expression had 5 year metastatic disease-free survival of ~ 60% vs. ~ 80% for men with high SPARCL1 expression." (PMID 29973149, 2018). "Several studies have described the role of SPARCL1 in the prognosis of colorectal, gastric, ovarian, and prostate cancers." (PMID 30987093, 2019). "In prostate cancer, SPARCL1 has been shown to suppress migration and invasiveness." (PMID 39548034, 2024). "The decreased SPARCL1 in prostate cancer promoted migration of cancer cells." (PMID 36483097, 2022). "However, the expression level of SPARCL1 was strongly decreased in most human cancers such as colorectal carcinoma, gastric cancer, and prostate carcinoma, suggesting the potential role to reduce cell proliferation and inhibit DNA synthesis." (PMID 36483097, 2022). "In addition, the prognostic impact of SPARCL1 expression in ovarian and prostate cancers has also been reported." (PMID 30987093, 2019). "Moreover, SPARCL1 can inhibit migration, invasion, and metastasis of prostate cancer." (PMID 37180578, 2023).
colon carcinoma (8 papers, 2006 to 2026). "Previous studies of SPARCL1 have identified associations with conditions such as Alzheimer’s disease, colon cancer, pulmonary hypertension, and pancreatic cancer." (PMID 41009953, 2025). "For instance, miR‐539‐3p acts as a tumor suppressor by inhibiting CDK14 in colon cancer cells, while it promotes ovarian cancer by targeting SPARCL1." (PMID 41584930, 2026). "Human SPARCL1 expression was downregulated in different carcinomas, including lung and colon cancers." (PMID 32437418, 2020). "SPARCL1, a known tumor suppressor of colon cancer, is an anti-adhesive extracellular matrix gene with anti-proliferative effects mediated through cell–cell adhesion." (PMID 28178989, 2017). "This gene was originally shown to be downregulated in human non-small cell lung cancer and subsequent reports indicated that downregulation of SPARCL1 also occurs in prostate and colon carcinomas." (PMID 16969345, 2006). "A study showed that SPARCL1 could inhibit tumor growth and liver metastasis in a mouse xenograft model and induce differentiation through mesenchymal-epithelial transition in colon cancer cells." (PMID 35111844, 2022). "Additionally, the expressions of SPARCL1, CP and TF differed significantly between stage IV colon cancer and normal (p < 0.05), while that of SPARCL1, CDH2, CP and SERPINA5 differed significantly between rectum adenocarcinoma and normal tissues." (PMID 34422629, 2021).
osteosarcoma (8 papers, 2018 to 2024). A usually aggressive malignant bone-forming mesenchymal neoplasm, predominantly affecting adolescents and young adults. "A prior investigation demonstrated that SPARCL1 recruits macrophages by activating the WNT/β‐catenin signalling pathway in osteosarcoma." (PMID 39548034, 2024). "A previous study verified the potential mechanism which explained why SPARCL1 can recruit macrophages in osteosarcoma." (PMID 36483097, 2022). "It has also been reported that DNA methylation is the reason for the downregulation of SPARCL1 and demethylation of the gene partially reversed the abnormal expression in pancreatic cancer and osteosarcoma." (PMID 30987093, 2019). "Similarly, it was reported in human osteosarcoma (OS) patients that higher SPARCL1 expression is positively correlated with M1 macrophage infiltration." (PMID 38762489, 2024). "Similarly, SPARCL1 was found to be a tumor suppressor in gastric cancer, osteosarcoma, pancreatic cancer, lung cancer, and renal cell carcinoma." (PMID 37180578, 2023). "Interestingly, a recent study is in accordance with our results, describing that Secreted Protein Acidic and Rich in Cysteine Like-1 (SPARCL1) protein suppresses osteosarcoma metastasis through activation of the Wnt/β-catenin signaling pathway." (PMID 34062831, 2021). "For instance, it was found that SPARCL1 was downregulated in osteosarcoma by epigenetic methylation of promoter DNA and activating the expression of SPARCL1 could inhibit the osteosarcoma metastasis in vitro and in vivo." (PMID 29760609, 2018). "VAMP8, A2M, HLA-DRA, SPARCL1, HLA-DQA1, APOC1 and AQP1 were identified continuously upregulating during the oncogenesis and metastasis of osteosarcoma." (PMID 32665038, 2020).
pancreatic cancer (8 papers, 2017 to 2025). "However, in contrast to its widespread expressed in normal tissues, downregulation of SPARCL1 has been reported as a putative tumor-suppressor factor in a wide variety of human malignancies including breast, colorectal, prostate and pancreatic cancers." (PMID 29973149, 2018). "Furthermore, a few reports have shown that SPARCL1 inhibited prostate, colorectal and pancreatic cancer cell migration and invasion in vitro/vivo, suggesting that SPARCL1 may be a potential suppressor of metastatic progression in many cancers." (PMID 29973149, 2018). "Elevation of LRG1, SPARCL1, S100A8, Plastin-2 may be of special significance in a small but significant percentage of patients which have increased risk for prolonged development of a disease spectrum that connects AP, RAP, and chronic pancreatitis with emergence of pancreatic cancer." (PMID 30214418, 2018). "Esposito and colleagues found that promoter demethylation slightly increased SPARCL1 mRNA, suggesting that hypermethylation is not the key mechanism accounting for low expression of SPARCL1 in pancreatic cancer cell." (PMID 29973149, 2018). "Besides, unlike the influence to colorectal and pancreatic cancer cells, SPARCL1 did not inhibit the proliferation of hilar cholangiocarcinoma cells and prostate cells in vitro." (PMID 29973149, 2018).
gastric cancer (7 papers, 2016 to 2023). A primary or metastatic malignant neoplasm involving the stomach. "A previous study found poor survival time of gastric cancer patients was linked with lower SPARCL1 transcriptional level, which was opposite to our analysis." (PMID 36483097, 2022). "Deregulation of protein expression, such as FN1 and ADAM9 (upregulated) or SPARCL-1 (downregulated), has been shown to affect cell growth and tissue proliferation in gastric cancer." (PMID 36672527, 2022). "In 2012, Li and colleagues reported that both SPARCL1 mRNA and protein levels were relevantly downregulated compared to normal tissues in a large series of patients harboring gastric cancer." (PMID 29973149, 2018). "Additionally, expression of SPARCL1 was closely associated with tumor grade, tumor size, regional lymph nodes, and TNM stages in gastric cancer." (PMID 29973149, 2018). "Since depletion of NKX6.3 in gastric epithelial cell lines induced CNAs and abnormal expression of SORBS2, SPARCL1, DLGAP5, and CDKN3, we examined NKX6.3 expression and these genes’ CNAs and expression in gastric cancer tissues." (PMID 34893582, 2021). "The expression levels of CDKN3 and DLGAP5 were markedly increased, whereas those of SPARCL1 and SORBS2 were decreased in 60 human gastric cancers." (PMID 34893582, 2021). "In contrast, SPARCL1 expression had negative effects on the prognosis in gastric cancer (HR = 1.27, p = 0.006)." (PMID 36483097, 2022). "In addition, the mRNA expression levels of CDKN3, DLGAP5, SPARCL1, and SORBS2 were positively correlated with CNAs in our gastric cancer samples." (PMID 34893582, 2021). "It was also important to examine the expression of FOG2, SPARCL1, and RUNX1t1 in normal human gastric mucosa, as no matching normal tissue samples were available from the initial human gastric cancer microarray analysis." (PMID 27522676, 2016). "In contrast, SPARCL1 expression had negative effects on the prognosis in gastric cancer." (PMID 36483097, 2022).
lung carcinoma (7 papers, 2014 to 2025). "For lung cancer, analysis of microarray data found a correlation between elevated SPARCL1 and a good survival time." (PMID 36483097, 2022). "PrognoScan data suggested that the good prognosis was verified to be associated with elevated SPARCL1 in a breast cohort, a prostate cohort, and a lung cancer cohort and decreased SPARCL1 in a colorectal cohort and an ovarian cancer cohort." (PMID 36483097, 2022). "Furthermore, a comparative proteomics analysis revealed that MUC5B, IQGAP, ENO1 and SPARCL1 were identified in the salivary exosomes of lung cancer patients." (PMID 40575159, 2025). "PrognoScan data suggested that SPARCL1 expression level might influence the survival time in some breast, colorectal, ovarian, prostate, and lung cancer cohorts." (PMID 36483097, 2022). "In contrast, NFKBIA, PSME3, SPARCL1, CCL15, and APOA1 did not return established entries under these filters and at the time of query, indicating that, within IPA, they are not currently categorized as clinical lung cancer biomarkers." (PMID 41465234, 2025).